NLRP3 (NLR family pyrin domain containing 3)
Diseases named in the same sentence as NLRP3 in open-access papers (continued):
Sharing a sentence is not in itself a finding about the gene and the disease.
depression (continued). "This is in light of substantial evidence supporting the role of the NLRP3 inflammasome in depression and cognitive dysfunctions, as well as the ability of different antidepressants to modulate this intracellular system." (PMID 39005130, 2025). "Substantial evidence indicates that the NLRP3 inflammasome is activated in the brain and blood samples of patients with depression." (PMID 40075143, 2025). "The NLRP3 inflammasome, a critical immune signaling platform, has been extensively investigated as a promising therapeutic target for the comorbidity of depression and CVD." (PMID 41194915, 2025). "In conclusion, the NLRP3 inflammasome represents not only a central molecular hub linking the comorbidity of depression and CVD, but also a promising therapeutic target that merits further research and clinical investigation." (PMID 41194915, 2025). "In mice subjected to chronic unpredictable mild stress (CUMS), which has been shown to yield the same effect as depression, levels of NLRP3 were increased in hippocampal regions." (PMID 40573262, 2025). "Inflammatory pathways, including the HMGB1/NLRP3 axis, contribute to the pathophysiology of depression." (PMID 40688353, 2025). "The NLRP3 inflammasome is expressed in key brain regions related to depression and is considered a potential biomarker of the disorder." (PMID 41199561, 2025). "Berberine reduces neuroinflammation by inhibiting the activation of NLRP3 inflammasome, thereby reversing neuroplastic damage and improved symptoms in depression model mice." (PMID 40735218, 2025). "The prevalence of both CVD and depression exhibits significant variations based on sex and age, which are closely correlated with the regulation of the NLRP3 inflammasome." (PMID 41194915, 2025). "It is understood that the maturation of IL-1β, which involves the cleavage of Caspase-1, relies on the NLRP3 inflammasome and significantly impacts depression." (PMID 40308754, 2025). "Another way by which NLRP3 inflammasome activation can induce depression is through the production of caspase-1." (PMID 40002529, 2025). "The metabolites include picolinic acid, a by-product of the kynurenine pathway which is down-regulated in depression; itaconic acid, which inhibits the NLR family pyrin domain containing 3 (NLRP3) protein; and α-linolenic acid." (PMID 40733008, 2025). "Meanwhile, exercise inhibits the activation of the NLRP3 inflammasome to reduce inflammatory responses, thereby improving mitochondrial energy metabolism and ultimately alleviating depression." (PMID 40699781, 2025). "The NLRP3 inflammasome functions as a critical link between CVD and depression, with shared underlying mechanisms in several areas." (PMID 41194915, 2025). "Stressors, pharmacological agents, and surgical interventions can all activate NLRP3, resulting in neuroinflammation, pyroptosis, and neuronal damage, which provides important evidence for the inflammatory mechanisms of depression." (PMID 41194915, 2025). "to alleviate depression-like behaviors in CUMS mice by targeting the GR/NF-κB/NLRP3 signaling pathway." (PMID 40936908, 2025). "Their results indicated neuroprotection against depression-related alterations and depressive behaviors through the mitigation of NLRP3 inflammasome activation." (PMID 40868122, 2025). "Evidence indicates that the NLRP3 inflammasome significantly contributes to the pathogenesis of depression by activating proinflammatory cytokines such as IL-1β and IL-18, which also play pivotal roles in the development of CVD." (PMID 41194915, 2025). "By amplifying inflammation, the HMGB1/NLRP3 axis contributes to both the onset and persistence of depression, positioning it as a potential therapeutic target for inflammation-related depression subtypes." (PMID 40688353, 2025).
depression (continued). "Anti-inflammatory psychopharmacology: Trials using low-dose anti-inflammatory agents (e.g., NSAIDs, minocycline, NLRP3 inhibitors) in depression offer a precedent for targeting inflammation in stress-linked psychiatric disorders." (PMID 40950762, 2025). "NLRP3 overactivation contributes to neurodegeneration across multiple conditions, such as depression, Alzheimer’s disease (AD), ischemic injury, and metabolic-associated cognitive decline, making it a major therapeutic target." (PMID 41357236, 2025). "This study is the first to reveal that geniposide exerts its antidepressant effects by upregulating lncRNA Six3os1, suppressing MAPK/NLRP3 pathway activation and inflammasome formation in a depression mouse model." (PMID 41341504, 2025). "NEK7 is under scrutiny for its regulatory role in NLRP3 activation in various diseases, including depression." (PMID 39005130, 2025). "Chronic mild stress (CMS) activates the NLRP3 inflammasome, enhances the maturation and release of IL-1β, and subsequently triggers neuroinflammation, ultimately leading to depression-like behavior." (PMID 40936908, 2025). "This activates NLRP3 inflammasomes in immune cells, exacerbates CNS inflammation, and triggers depression-like behavior." (PMID 40936908, 2025). "Previous studies have demonstrated that NLRP3 inhibitors can significantly ameliorate pathological manifestations in models of depression and CVD, underscoring their potential as dual therapeutic targets." (PMID 41194915, 2025). "This review summarizes the role of the NLRP3 inflammasome in the mechanisms of CVD-depression comorbidity and explores the potential and challenges of targeting the NLRP3 inflammasome for the treatment of this condition." (PMID 41194915, 2025). "The administration of P2X7R antagonists, a P2X7R knockout, or the inhibition of NLRP3 inflammasome activity can alleviate chronic stress-induced depression-like behaviors in rats." (PMID 38642324, 2025). "Berberine improves depression-like behavior in mice by inhibiting the activation of the NLRP3 inflammasome and rescues neuronal damage by preventing synaptic plasticity and neurogenesis impairments." (PMID 40075143, 2025). "In diabetes with comorbid depression, EE alleviated depressive-like behavior, improved glucose regulation, reduced neuronal apoptosis, and suppressed microglial NLRP3 alongside PI3K/AKT pathway restoration, a negative regulator of inflammasome activation." (PMID 41357236, 2025). "For example, activated NLRP3 inflammatory vesicles can promote depression by prompting microglia to activate indoleamine 2,3-dioxygenase (IDO) and exacerbate neuroinflammation through kynurenine pathway signaling." (PMID 40497971, 2025). "Meta-analyses now place psychobiotics alongside anti-cytokine biologics (e.g., infliximab) and small-molecule NLRP3 inhibitors as emerging options for inflammation-biased depression." (PMID 41373485, 2025). "Previous experiments have shown that DACA has effects similar to those of HMGB1 inhibitors in suppressing the HMGB1/NF‐κB/NLRP3 pathway, thereby alleviating depression." (PMID 40406924, 2025). "Mice undergoing oophorectomy experience a decrease in estrogen levels, leading to an increase in P2X7R expression, and IL-1β,IL-18,NLRP3 inflammasome activation leads to hippocampal neuroinflammation and depression." (PMID 38642324, 2025). "Substances such as natural polyphenols, N-acetylcysteine, and MCC950 show therapeutic promise for both CVD and depression by inhibiting NLRP3 inflammasome activation." (PMID 41194915, 2025). "This study reveals that gut flora can modulate ethanol exposure-induced depressive disorders through peripheral inflammation and hippocampal NLRP3 inflammatory vesicles." (PMID 40357036, 2025). "Regardless, the role of NLRP3 in inflammation and depression warrants further investigation in MS animals." (PMID 38672480, 2024).
depression (continued). "The gut microbiota of NLRP3 KO mice regulated astrocyte dysfunction via circHIPK2, attenuating depressive-like behaviors and providing a novel strategy for the treatment of depression." (PMID 38983862, 2024). "Modulating the NLRP3 inflammasome to diminish pyroptosis is essential for effective depression management." (PMID 39263574, 2024). "Consistent with our findings, activation of the NLRP3 inflammasome was observed in AMI rats with depression, leading to the cleavage of GSDMD and subsequent release of IL‐18 and IL‐1β, thereby promoting microglial pyroptosis." (PMID 38970230, 2024). "The upregulation of NLRP3 inflammasome is related to the occurrence of depressive symptoms, and inhibiting NLRP3 inflammasome is an effective method for the treatment of depression." (PMID 39036341, 2024). "Previous results have shown that activated NLRP3 is the essential factor in the pathogenesis of depression and anxiety." (PMID 39555096, 2024). "Considering this information, our study observes that the physiopathology of depression‐like behavior after ovariectomy includes an increase in NLRP3 and IL‐1β levels and a decrease in BDNF levels in the hippocampal area." (PMID 39443283, 2024). "Inhibition of NLRP3 inflammasome and downstream cytokines is an emerging study topic in many animal models of stress induction, anxiety and depression further elucidating the PNI pathophysiology of psychiatric disorders." (PMID 39624485, 2024). "Fingolimod is reported to regulate NLRP3 and microglia activation, leading to chronic and unpredictable depression-like behavior induced by mild stress." (PMID 38643466, 2024). "Depression-like behavior in rodents highly correlates with inflammatory responses in the central nervous system, and NF-κB/NLRP3 pathway activation is generally considered the initial inflammatory response." (PMID 38720779, 2024). "Previous investigations have revealed the activation of the NLRP3 inflammasome in blood cells obtained from patients suffering from depression." (PMID 38916735, 2024). "Fluoxetine, an SSRI used for depression, effectively inhibits NLRP3-ASC inflammasome activation and the release of inflammatory cytokines in retinal pigment epithelium (RPE) cells and macrophages, potentially mitigating dry AMD." (PMID 38892791, 2024). "Among the various inflammasomes, the NLR family pyrin domain-containing 3 (NLRP3) inflammasome plays a crucial role in the pathophysiology of depression." (PMID 38911248, 2024). "Most animal studies have shown that the activation and inhibition of NLRP3 inflammasome by gut microbiota can regulate depression‐like behavior and affect hippocampal neuroinflammation and glial cell function in rodents." (PMID 39036341, 2024). "The RvD1, NLRP3, IL-1β, IL-18, and IL-4 serum levels were dynamically evaluated before and after 6-8-week anti-depression treatment." (PMID 38627683, 2024). "However, an overactivated NLRP3 inflammasome induces procaspase‐1 self‐cleavage and activation, causing maturation of pro‐inflammatory cytokines and release of inflammatory factors, causing central nervous system disorders, and promoting the progression of inflammatory diseases such as depression." (PMID 38752512, 2024). "There are also many research reports on the treatment of depression by targeting the NLRP3 inflammasome." (PMID 37559243, 2024). "In a CUMS depression model, ferulic acid treatment has been observed to suppress microglial activation, NF-κB signaling, and NLRP3 inflammation." (PMID 38306547, 2024). "NLRP3 inflammasome-mediated neuroinflammation is closely related to the pathogenesis of some mental disorders, such as depression." (PMID 38791415, 2024).
depression (continued). "Hesperidin improves chronic and unpredictable mild stress-induced depression by inhibiting inflammation of microglia and regulating NLRP3 validation signaling pathway." (PMID 38643466, 2024). "At the end of the experimental procedure, MDA, GSH, BDNF, IL‐1B, and NLRP3 levels were analyzed in the hippocampus to analyze the physiopathological mechanism of menopause‐related depression and the therapeutic effects of valsartan on these mechanisms." (PMID 39443283, 2024). "Further studies will be needed to clarify the role of NLRP3 inflammatory and gut microbiota on the pathogenesis of UC-related depression in mice." (PMID 38393047, 2024). "P2X7R inhibition or deficiency prevented NLRP3 inflammasome activation and the production of IL-1β, suggesting a potential mechanism for P2X7R in mediating atrial remodelling in depression." (PMID 38261756, 2024). "Studies have shown that the NLRP3 inflammasome plays an important role in the occurrence of depression." (PMID 38538614, 2024). "Several treatments targeting the NLRP3 pathway attenuate chronic-stress-induced IL-1β levels and improve anxiety-like and depression-like behaviors." (PMID 38791125, 2024). "The nucleotide-binding oligomerization structural domain-like receptor protein 3 (NLRP3) inflammatory pathway plays a crucial role in the initiation and progression of depression." (PMID 38389919, 2024). "The findings revealed that the transplanted wild-type mice displayed depression and anxiety-like behaviors, whereas the NLRP3 gene knockout mice exhibited milder manifestations of these behaviors compared to the wild-type mice." (PMID 38449739, 2024). "Ultimately, chronic stress significantly increases IL-18 in the HPC, PFC, HYP, and periphery, which can be reduced by various treatments that suppress the expression of the NLRP3 inflammasome and attenuate depression-like behaviors." (PMID 38791125, 2024). "NLRP3 inflammasome, an important downstream effector of P2X7R, has been implicated in the pathogenesis of depression and AF." (PMID 38261756, 2024). "Ferulic acid inhibited the activation of microglia and significantly decreased the contents of IL-1β, IL-6, and TNF-α in the prefrontal cortex of the CUMS-induced depression mouse model by inhibiting the NLRP3/caspase-1/NF-κB pathway." (PMID 38915473, 2024). "Rapamycin, an inhibitor of mTOR signaling, has been reported to alleviate the symptoms of seizures, anxiety, and depression in PTZ-kindled rats by inhibiting NLRP3 inflammasomes and ROS production." (PMID 38892264, 2024). "The objective of this research is to explore the impact of AT1RB therapy on depression and anxiety‐like behaviors triggered by menopause, as well as the levels of NLRP3, IL‐1β, BDNF, and oxidative stress in the hippocampal and prefrontal cortex tissues." (PMID 39443283, 2024). "Extracellular ATP (eATP) signaling through the P2X7 receptor pathway is widely believed to trigger NLRP3 inflammasome assembly in microglia, potentially contributing to depression." (PMID 38890305, 2024). "Many compounds reduce IL-18 expression through the modulation of the NLRP3 pathway, resulting in attenuated depression-like behaviors." (PMID 38791125, 2024). "Of all inflammasomes, the NOD-, leucine-rich repeat (LRR)-, and pyrin domain (PYD)-containing protein 3 (NLRP3) inflammasome has been studied extensively and proposed to be a potential target for the treatment of depression." (PMID 37559243, 2024). "Previous findings have demonstrated that extracellular ATP (eATP) acts as a stress signal via P2X7 receptors (P2X7Rs) to induce NLRP3 inflammasome assembly, an important event in the pro-inflammatory status of hippocampal microglia in depression development." (PMID 38890305, 2024). "For example, a recent study evaluated levels of the NLRP3 inflammasome and IL-1β in patients with MI and depression." (PMID 39590595, 2024).
depression (continued). "Research has shown that acupuncture can prevent CMS-induced depression-like behavior by inhibiting the NF-κB/NLRP3 inflammatory pathway." (PMID 39367470, 2024). "Given the critical role of NLRP3 in gut-immune-brain communication, deciphering the role and dysfunction of NLRP3 is crucial for depression." (PMID 38983862, 2024). "Activation of NLRP3 and increased secretion of IL-1β and IL-18 are essential pathophysiological mechanisms of depression." (PMID 38627683, 2024). "Recent evidence suggests that neuroinflammation is a key mediator of depression, and, in particular, the expression of pro-inflammatory factors such as NLRP3 and IL-1β is significantly enhanced in depressed patients." (PMID 39770545, 2024). "We assessed effects of JSO on c-GAS-Sting-NLRP3 axis-mediated inflammation in CRS-induced depression and anxiety by WB." (PMID 39555096, 2024). "NLRP3 activation occurs in major depressive patients and experimental studies have shown that it is effective in the formation of depression‐like behavior." (PMID 39443283, 2024). "TLR4 and NF-κB, important regulators of NLRP3-complex priming, were also increased, which further confirmed the inflammation condition in atria of depression." (PMID 38261756, 2024). "Two signaling pathways involved in the NLRP3 inflammasome activation have been described in depression: the priming process and the protein complex assembly one." (PMID 38791415, 2024). "A previous study showed that resveratrol activated sirtuin-1 in OVX mice, reducing anxiety and depression-like behaviors by inhibiting the hippocampus’s NF-κB and NLRP3 signaling pathways, thereby preventing neuroinflammatory processes." (PMID 38306547, 2024). "The NF-κB/NLRP3 axis has been confirmed to be activated in both depression models and individuals diagnosed with depression." (PMID 38911248, 2024). "We were not able to detect a concurrent contribution of IL-1β and IL-18 to the likelihood of depression, possibly because of their involvement in the NLRP3-independent pathways." (PMID 37763063, 2023). "TET2 deficiency activates the NLRP3/IL-1β pathway of microglia in the ACC, promoting the pathological process of anxiety and depression-like behavior in AR." (PMID 38012545, 2023). "In conclusion, our study reveals that NLRP3 inflammasome activation and pyroptosis as well as abnormal mitochondrial morphology and function occur in the hippocampus of the LPS-induced depression-like mouse model." (PMID 37626978, 2023). "As mentioned, NLRP3 inflammasome activation occurs in the CNS in the LPS-induced depression-like mouse model." (PMID 37626978, 2023). "Treatment of acidic polysaccharides from poria improved the depression-like behavior, increased the number of neurons and the levels of neurotransmitters in the hippocampus, regulated NLRP3 inflammasome signaling pathway in depression model rats." (PMID 38075226, 2023). "The roles of the NLRP3 inflammasome in the pathogenesis of depression have also been reported recently, and astrocytes shifted to the neurotoxic state in depression." (PMID 36675113, 2023). "Our data demonstrated that thalamic HIF-1α/NLRP3 inflammatory signaling was responsible for the comorbid anxiety and depression in CPSP rats." (PMID 36944982, 2023). "Melatonin can improve LPS-induced acute depression-like phenotype by suppressing the activation of the microglial NLRP3 inflammasome, thus reducing the pro-inflammatory factors released by microglia." (PMID 37881439, 2023). "As revealed by western blotting and immunofluorescence labeling, the current data suggest that the NLRP3 signaling pathway was activated in CORT-induced depression mice, while berberine downregulated the NLRP3 signaling pathway in the hippocampus and PFC." (PMID 36859349, 2023). "Together, these results confirmed that NLRP3 was involved in the process of neuroinflammation and served as a modulator in the development of depression." (PMID 36859349, 2023).